CCDC54 (coiled-coil domain containing 54)
Synonyms: NYD-SP17; FLJ25362; SP17
Tractability: No criterion of Open Targets' tractability assessment is met for any kind of drug.
Gene: Protein-coding gene on chromosome 3 (107,377,439 to 107,378,635, forward strand). Ensembl gene ENSG00000138483.
Genetic constraint (gnomAD): Loss-of-function variants: 11 observed, 11.46 expected, observed/expected ratio (o/e) 0.96, 90% interval 0.6 to 1.57. The upper end of that interval is the gene's LOEUF score, 1.57, which puts it in group 6 of 6, group 1 being the genes least tolerant of losing a copy. Missense variants: 368 observed, 399.38 expected, observed/expected ratio (o/e) 0.92, 90% interval 0.85 to 1. Synonymous variants: 128 observed, 137.46 expected, observed/expected ratio (o/e) 0.93, 90% interval 0.81 to 1.08.
Homologues: Orthologues: chimpanzee CCDC54 (98% identical), macaque CCDC54 (93% identical), dog CCDC54 (75% identical), pig CCDC54 (72% identical), rat Ccdc54 (65% identical), mouse Ccdc54 (65% identical), rabbit CCDC54 (60% identical).
Diseases named in the same sentence as CCDC54 in open-access papers:
CCDC54 is named in the same sentence as 2 diseases in open-access papers, as found by Europe PMC text mining. Sharing a sentence is not in itself a finding about the gene and the disease. The quoted sentences say what the papers report.
cancer (1 paper, 2008). A tumor composed of atypical neoplastic, often pleomorphic cells that invade other tissues. "In addition, the testes development-related gene CCDC54 (P = 3.3×10−4) is currently a target of cancer immunotherapy research." (PMID 18670650, 2008).
CCDC54 also shares sentences with these, for which no sentence is quoted: oligospermia (1 paper).